HUWE1 (HECT, UBA and WWE domain containing E3 ubiquitin protein ligase 1)
Diseases named in the same sentence as HUWE1 in open-access papers (continued):
Sharing a sentence is not in itself a finding about the gene and the disease.
tumor (continued). "Interestingly, Myc deletion does not impact on the increased tumour initiation phenotype; rather, it dampens the elevated tumour cell proliferation observed in Huwe1‐deficient tumours." (PMID 28003334, 2017). "Importantly, this increased DNA damage phenotype sensitises Huwe1‐deficient tumours to treatment with DNA‐damaging agents and depletion of the anti‐apoptotic protein MCL1." (PMID 28003334, 2017). "The E3 ubiquitin ligase HUWE1, deregulated in carcinoma, has been implicated in tumor formation." (PMID 25543140, 2015). "Specifically, in BC cells, KAT8‐mediated YEATS4 acetylation at K64, 65, and 69 promotes YEATS4 stabilization by blocking its HUWE1‐dependent degradation, which in turn contributes to DNA repair and tumor growth and consequently results in DDP resistance." (PMID 38526153, 2024). "Since some HUWE1 substrates are oncoproteins and others are tumor suppressors, HUWE1 can be either oncogenic or tumor suppressing, mainly depending on the leading substrates it regulates in the context." (PMID 37813845, 2023). "Previous studies have shown that HUWE1 was overexpressed in CRC tumor tissues, and HUWE1 expression directly correlates with tumor progression." (PMID 36831013, 2023). "On the other hand, MAGEA11 recruits HUWE1 E3 ubiquitin ligase for modulating core oncogenic and tumour suppressor pathways." (PMID 38136576, 2023). "The function of HUWE1 in tumor growth or inhibition rarely depends on the cell type and is mediated through different mechanisms." (PMID 35937685, 2022). "This study demonstrated that both c-Myc and Miz1 are direct targets of HUWE1 and that HUWE1 functions as a tumor suppressor." (PMID 35937685, 2022). "This study identified HUWE1 as functioning as a bona fide tumor suppressor by inhibiting tumor initiation." (PMID 35937685, 2022). "HUWE1 has been reported to be highly expressed in colorectal, lung, stomach, ovarian, and breast carcinoma and able to inhibit tumor growth by mediating the degradation of the Myc/Miz complex in a mouse skin cancer model." (PMID 35107378, 2022). "HUWE1 is highly conserved in mammals and was originally identified as a major binding protein associated with the ARF (ADP-ribosylation factor) tumor suppressor." (PMID 35107378, 2022). "The activation of JNK, either by EGFR or chemotherapy agent, stabilizes BMI1 and MCL1 protein expressions through suppressing HUWE1 expression, which then promote tumour initiation and chemo‐resistance." (PMID 35794816, 2022). "This study revealed HUWE1 as functioning as a critical tumor suppressor by modulating the cellular apoptotic response to HDAC inhibition and DNA damage." (PMID 35937685, 2022). "This study indicated that HUWE1 acts as a tumor suppressor by mediating Cdc6 degradation and driving cell cycle arrest and apoptosis during the DNA damage response." (PMID 35937685, 2022). "HUWE1 is a two-faced ligase with respect to cancer, as depending on the type of cancer it will act either as an enhancer or a tumor suppressor." (PMID 34577077, 2021). "This work suggests a tumour suppressive role for Huwe1 in GSCs, however, more research is required to elucidate this fully." (PMID 33432111, 2021). "Binding of HUWE1 with the p14ARF tumor suppressor has namely been reported to shift this conformational equilibrium toward the inactive state." (PMID 34065298, 2021). "In GB, Huwe1 is often downregulated and focal deletions of Huwe1 have been reported in 25% of n-Myc amplified tumours." (PMID 33432111, 2021). "Overexpression of HUWE1 has been identified in many cancers, with one study reporting increased expression of HUWE1 in 7 out of 9 tumor types." (PMID 32523091, 2020).
tumor (continued). "Accordingly, application of inducible HUWE1 knockdown in an MM1.S xenotransplantation model showed for the first time that blockade of HUWE1 expression is also effective at slowing tumour growth in vivo." (PMID 33116152, 2020). "While this combination only produced a modest effect on viability in vitro, MM tumour growth in vivo continually decreased over the length of the study indicating that knockdown of HUWE1 sensitized the cells to melphalan-induced cell death." (PMID 33116152, 2020). "In summary, accumulating evidence points to a context-dependent role for HUWE1 in tumor pathogenesis." (PMID 32523091, 2020). "In one model, HUWE1 regulates the stability of MYC through K48-linked ubiquitination and knockdown of HUWE1 leads to increased MYC and drives tumor progression." (PMID 32523091, 2020). "By employing proteomics, we further demonstrated that several members of the ubiquitin signaling machinery are deregulated in both tumor and LN metastatic lesions and interestingly, we detected high HUWE1 expression in RET transformed cells." (PMID 32345963, 2020). "Concomitant melphalan application and HUWE1 knockdown resulted in robust suppression of tumour growth (at day 7 post knockdown induction: 10.00 × 108 ± 1.12 × 108 photons/sec vs 38.09 × 108 ± 12.07 × 108 photons/sec in the melphalan-only control group)." (PMID 33116152, 2020). "HUWE1 mediated K63-linked ubiquitination of HK2 promotes its re-localization and activation, enhancing glycolysis and tumor growth." (PMID 33004065, 2020). "We have extended the proteomic analysis further to 4 more patients and we consistently identified HUWE1 as one of the prime factors that are upregulated in the tumor and metastatic lesions." (PMID 32345963, 2020). "Conversely, in other tumor types HUWE1 activates transcription of MYC through K63-linked ubiquitination and HUWE1 silencing or inhibition prevents MYC signaling and reduces tumor cell proliferation." (PMID 32523091, 2020). "At day 7 post-inoculation the control group displayed significantly larger tumour mass than the HUWE1 knockdown group (22.14 × 109 ± 4.70 × 109 vs. 13.98 × 109 ± 5.61 × 109 photons/sec)." (PMID 33116152, 2020). "Combinations of HUWE1 inhibition and the IMiD lenalidomide, in particular, lead to significantly reduced tumor growth both in vitro and in vivo." (PMID 32523091, 2020). "HUWE1 was identified as crucial for the tumorigenicity of cancer cells, and its genetic or pharmacologic targeting resulted in the collapse of tumor cells." (PMID 30261639, 2018). "Interaction between the tumor suppressor p14ARF and the activation segment promotes oligomerization of HUWE1, therefore shifting the conformational equilibrium of HUWE1 toward the inactive state." (PMID 30176860, 2018). "In fact, HUWE1 has been described as a tumour suppressor gene controlling the proto-oncogene c-Myc regulation." (PMID 30217973, 2018). "Numerous studies have shown that HUWE1 can be either oncogenic or tumor suppressing, depending on the leading substrates that it regulates in the context [see “Substrates of HUWE1”]." (PMID 30176860, 2018). "HUWE1 mediates ubiquitination and degradation of histone H1.3 has been reported to regulate normal ovarian epithelial cell transformation and tumor growth." (PMID 30176860, 2018). "Consistent with our previous model, Huwe1 deletion led to a dramatic shortening of lifespan and a marked increase in tumour number and increased tumour cell proliferation (and EV4A and B)." (PMID 28003334, 2017). "Our work shows, by robust genetic characterisation, that Huwe1 is a tumour suppressor in the small intestine and colon." (PMID 28003334, 2017).
tumor (continued). "Strikingly, in the context of Huwe1 deletion, reduced expression of Myc led to a significant increase in survival, thus indicating that the tumour suppressor function of HUWE1 is, at least in part, mediated through the control of MYC stability." (PMID 28003334, 2017). "Surprisingly, both pro-oncogenic and tumor-suppressor functions of HUWE1 have been documented in different tumor models." (PMID 28193319, 2017). "We found that patients whose tumours express low levels of HUWE1 have significantly increased overall survival following chemotherapy treatment than those expressing higher levels." (PMID 28003334, 2017). "We find inactivating HUWE1 mutations in human CRC and that deletion of Huwe1 in CRC mouse models leads to rapid tumourigenic and hugely increased tumour initiation." (PMID 28003334, 2017). "They did, however, show decreased tumour proliferation rates compared to tumours from Vil Apc Pten Huwe1 mice (Fig EV4A and B)." (PMID 28003334, 2017). "More importantly, all tumours lost the second copy of Apc, and once this occurred, WNT target expression was similar between wild‐type and Huwe1‐deficient intestines." (PMID 28003334, 2017). "Together, these data define HUWE1 as a critical intestinal tumour suppressor gene that restrains cellular proliferation and DNA damage accumulation." (PMID 28003334, 2017). "Taken together, our studies lay out an unprecedented mechanistic framework for the conformational regulation of HUWE1 and its interactions with the tumor suppressor p14ARF." (PMID 28193319, 2017). "Further investigation revealed that HUWE1 was a direct target of miR-542-5p, and that reduced expression of this protein played an important role in the tumor-promoting effect of miR-542-5p overexpression." (PMID 26498360, 2015). "We propose here thattargeting the HUWE1 ubiquitin ligase is feasible and allows for a tumor cell-specific inhibition ofMYC function." (PMID 25253726, 2014). "First, as predicted, knockdownof HUWE1 effectively blocked colorectal cancer cell growth ex vivo and,importantly, blocked the progression of tumor xenografts in vivo." (PMID 25368331, 2014). "In contrast, depletion of HUWE1 in several human tumor cells arrestsproliferation and inhibits expression of MYC-activated target genes (Adhikaryet al, 2005)." (PMID 25253726, 2014). "The E3 ubiquitin ligase HUWE1 modifies a diverse network of substrate proteins by ubiquitination, through which it regulates various intracellular processes and contributes to both oncogenic and tumour suppressor mechanisms in different cancer contexts." (PMID 41942468, 2026). "Previous studies implicate HUWE1 in inflammasome assembly, hepatic iron metabolism, and tumor progression, but its role in HCC remains unclear." (PMID 40914145, 2025). "Eliminating or reducing the activity of HUWE1 itself, which in turn reduces WNT/CTNNB1 signaling in WT HAP1-7TGP, CSNK1A1KO and CTNNB1ST-A cells, is unlikely to be a viable therapeutic strategy due to the multiple roles of HUWE1 on cell physiology, including tumor suppressor functions." (PMID 40424469, 2025). "Although HUWE1 has been shown to mediate the turnover of MUTYH in tumor cells, its role in AKI remains unknown." (PMID 39921445, 2025). "Eliminating or reducing the activity of HUWE1 itself, which reduces WNT/CTNNB1 signaling in WT HAP1–7TGP, CSNK1A1KO and CTNNB1ST-A cells, is unlikely to be a viable therapeutic strategy due to the pleiotropic effects of HUWE1 on cell physiology, including tumor suppressor functions." (PMID 38410441, 2024). "The reason for the opposite function of HUWE1 in tumor may be the different tumor microenvironment and genetic backgrounds." (PMID 37700273, 2023). "Furthermore, HUWE1 exhibits ligase activity in multiple cell types, including epithelial cells, tumor cells, neural cells, stem cells, germ cells, and immune cells." (PMID 35937685, 2022).
tumor (continued). "HUWE1 contributed to tumor growth by promoting endogenous DNA damage repair, and targeting HUWE1 might be a potential therapeutic approach for MM." (PMID 35937685, 2022). "Likewise, HUWE1 genetic inhibition, in combination with chemotherapy, was shown to counteract tumor growth in vivo, suggesting that HUWE1 sustains tumorigenesis and that its deregulation would improve the efficacy of standard of care therapies." (PMID 36140335, 2022). "In fact, HUWE1 can act as either an oncogene or tumor suppressor depending on the type of cancer, and the association between HUWE1 expression and overall survival is not clear for most cancers." (PMID 35937685, 2022). "In this manuscript, we review the roles of HUWE1 in multiple aspects, discuss the controversial finding that HUWE1 can be considered either an oncogene or tumor suppressor, and present the challenges in therapeutic strategies targeting giant E3 ligases such as HUWE1." (PMID 35937685, 2022). "HUWE1 works as an important tumor suppressor through inhibiting the Ras-induced tumorigenesis." (PMID 36167633, 2022). "Thus, HUWE1 functions as a tumor suppressor to inhibit neuronal proliferation and promote neurogenesis." (PMID 35937685, 2022). "In addition, HUWE1 has been demonstrated to play contradictory roles in certain aspects of tumor progression in either an oncogenic or a tumor-suppressive manner." (PMID 35937685, 2022). "Additionally, tumor suppressor p14ARF works as a HUWE1 inhibitor by interacting with that small amino acid segment and hijacking the enzyme in the auto-inhibited dimer conformation." (PMID 34577077, 2021). "Therefore, additional studies, including in vivo experiments using spontaneous cancer mouse models, are needed to better understand the tumor suppressing functions of HUWE1 mediated by elimination of autophagy proteins." (PMID 34502089, 2021). "Moreover, HUWE1 is in charge of the ubiquitination of tumor-involved histone H1.3, or physiologically involved histones H1 and H3, amongst others." (PMID 34577077, 2021). "HUWE1 acts as both an oncogene and tumor suppressor depending on cell context." (PMID 32523091, 2020). "Furthermore, knockdown of HUWE1 significantly reduces tumor burden in an aggressive in vivo model of MM validating its potential as a therapeutic target in MM." (PMID 32523091, 2020). "We identified a number of other metabolic enzymes and transporters as potential substrates of HUWE1, suggesting that, in MM, HUWE1 may exhibit a broader effect on tumor metabolism." (PMID 32523091, 2020). "Whether HUWE1 possesses tumor promoting or tumor suppressor activity is a matter of debate and appears to be dependent on cell type." (PMID 32523091, 2020). "Furthermore, the combination of HUWE1 knockdown and lenalidomide significantly reduced tumor burden compared with either treatment alone (p = 0.03)." (PMID 32523091, 2020). "This is consistent with previous studies observing HUWE1 overexpression in primary tumor samples." (PMID 31905981, 2019). "While some of HUWE1’s substrates are tumor suppressors, others are known to promote cell survival." (PMID 31905981, 2019). "HUWE1 participates to c-Myc degradation, leading to a reduction in tumour diffusion." (PMID 30217973, 2018). "Furthermore, both oncogenic and tumor suppression roles were previously reported for the HUWE1 gene." (PMID 29402894, 2018). "HUWE1 is a critical ubiquitination modulator during the tumor progression and may serve as a possible therapeutic target for cancer treatment." (PMID 30176860, 2018). "CUL4A-DDB1 tandem functions as an oncogene, HUWE1 has rather a tumor suppressor activity." (PMID 29983883, 2018).
tumor (continued). "Thus, our findings are consistent with a tumour‐suppressive role of HUWE1 in destabilising MYC post‐translationally." (PMID 28003334, 2017). "Our studies reveal, intriguingly, that the tumor suppressor p14ARF binds to this segment and may thus shift the conformational equilibrium of HUWE1 toward the inactive state." (PMID 28193319, 2017). "Thus, we think it is most likely that tumours arise due to different tumour‐suppressive mechanisms exerted by HUWE1." (PMID 28003334, 2017). "Given this profound impact on tumour formation, we next analysed whether Huwe1 deletion impacted on intestinal homoeostasis." (PMID 28003334, 2017). "This increase in MYC protein was also observed in Huwe1‐deficient Vil Apc Huwe1 tumours compared to controls and was independent of transcriptional effects." (PMID 28003334, 2017). "As MYC is a critical modulator of intestinal tumourigenic, we hypothesised that the modulation of MYC stability may be a key tumour‐suppressive function of HUWE1 within the gut." (PMID 28003334, 2017). "Moreover, HUWE1 has been intensely studied in context of cancer, where it was assigned pro-oncogenic but also tumor-suppressive functions." (PMID 28943312, 2017). "Importantly, by dissecting the mechanism via which Huwe1 suppresses colonic tumourigenic, we identify a potential vulnerability of these tumours to DNA‐damaging agents and anti‐apoptotic inhibitors." (PMID 28003334, 2017). "Rather, we observed an ~40‐fold increase in tumour number together suggesting changes in EPHB3 stabilisation are not the primary cause of tumour initiation following Huwe1 deletion." (PMID 28003334, 2017). "This has the consequence of slowing the accelerated tumour growth following Huwe1 loss but has no impact on the ability of tumours to form." (PMID 28003334, 2017). "Thus, tumour cell survival in the context of increased DNA damage following Huwe1 deletion is partially dependent on increased levels of MCL1." (PMID 28003334, 2017). "Thus far, evidence from cell line and xenograft studies exists to support both models, but genetic evidence from a skin cancer model showed Huwe1 deletion accelerated tumourigenic suggesting a tumour suppressor role." (PMID 28003334, 2017). "Importantly, Huwe1 is strongly down regulated in tumor-prone Ptch1+/− heterozygous mice, and low HUWE1 expression is associated with poor prognosis only within the SHH subgroup of human MB." (PMID 25008045, 2014). "Interestingly, in CRC, whether HUWE1 (also named Mule, HectH9, ARF-BP1, HSPC272, Ib772, URE-B1, E3 Histone, and LASU1) functions as a tumor promoter or a tumor suppressor remains controversial." (PMID 36831013, 2023). "Thus, either the HUWE1/ATG101 or HUWE1/WIPI2 pathway could be potential targets for suppressing tumor cell survival, and these reverse combinational approaches may be more effective." (PMID 34502089, 2021). "Thus, activation of this HUWE1/ATG101 pathway may be a feasible clinical strategy to impair cancer cell survival or enhance the efficacy of anti-tumor therapies." (PMID 34502089, 2021). "On the one hand, HUWE1 is able to enhance tumor cell proliferation by K63-poly ubiquitination and activation of the transcription regulator MYC, on the other hand, depletion or mutation of HUWE1 lead to increased MYC levels, thereby promoting skin and colon tumorigenesis." (PMID 31001145, 2019). "Moreover, we did not observe tumour formation in intestines deficient for Huwe1 alone, even a year post‐induction suggesting that disruption of homoeostasis (e.g. deregulation of stem cell markers and Paneth cells) was not sufficient in driving carcinogenesis." (PMID 28003334, 2017). "Thus, increased DNA damage appears to be a property of HUWE1 mutation in human CRC and may confer a therapeutic vulnerability on these tumours during tumourigenic." (PMID 28003334, 2017).